CANT1 (calcium activated nucleotidase 1)
Description:
Calcium-dependent nucleotidase with a preference for UDP. The order of activity with different substrates is UDP > GDP > UTP > GTP. Has very low activity towards ADP and even lower activity towards ATP. Does not hydrolyze AMP and GMP. Involved in proteoglycan synthesis.
Synonyms: SCAN-1; SHAPY; DBQD; DBQD1; EDM7; SCAN1
Tractability: Small molecule: a structure with a bound ligand is known; it has a high-quality binding pocket. Antibody: UniProt places it where antibodies can reach, with high confidence; its Gene Ontology location is reachable by antibodies, with high confidence; UniProt predicts a signal peptide or a membrane-spanning region. PROTAC: ubiquitination databases record sites on it; its protein half-life has been measured.
Gene: Protein-coding gene on chromosome 17 (78,991,707 to 79,009,867, reverse strand). Ensembl gene ENSG00000171302.
Subcellular location: Endoplasmic reticulum membrane; Golgi apparatus, Golgi stack membrane; Cell membrane
Subcellular location (Human Protein Atlas): Golgi apparatus
Pathways (Reactome):
Immune System: Neutrophil degranulation
Gene Ontology:
Molecular function: ADP phosphatase activity; calcium ion binding; GDP phosphatase activity; IDP phosphatase activity; nucleoside diphosphate phosphatase activity; protein binding; protein homodimerization activity; UDP phosphatase activity
Biological process: positive regulation of canonical NF-kappaB signal transduction; proteoglycan biosynthetic process
Cellular component: endoplasmic reticulum membrane; extracellular exosome; Golgi apparatus; membrane; plasma membrane; extracellular region; ficolin-1-rich granule lumen; specific granule lumen; tertiary granule lumen; Golgi cisterna membrane
Genetic constraint (gnomAD): Loss-of-function variants: 28 observed, 30.97 expected, observed/expected ratio (o/e) 0.9, 90% interval 0.67 to 1.24. The upper end of that interval is the gene's LOEUF score, 1.24, which puts it in group 5 of 6, group 1 being the genes least tolerant of losing a copy. Missense variants: 518 observed, 554.7 expected, observed/expected ratio (o/e) 0.93, 90% interval 0.87 to 1. Synonymous variants: 246 observed, 245.41 expected, observed/expected ratio (o/e) 1, 90% interval 0.9 to 1.11.
Gene-disease validity (ClinGen):
ClinGen rates the evidence that CANT1 causes each of these diseases.
Desbuquois dysplasia 1 (autosomal recessive): Definitive.
Homologues: Orthologues: chimpanzee CANT1 (99% identical), macaque CANT1 (97% identical), mouse Cant1 (88% identical), guinea pig CANT1 (87% identical), rat Cant1 (87% identical), pig CANT1 (87% identical), tropical clawed frog cant1 (75% identical), dog CANT1 (71% identical), zebrafish cant1a (69% identical), zebrafish cant1b (64% identical), Drosophila melanogaster CG5276 (46% identical), Caenorhabditis elegans apy-1 (39% identical), and 1 more.
Diseases named in the same sentence as CANT1 in open-access papers:
CANT1 is named in the same sentence as 41 diseases in open-access papers, as found by Europe PMC text mining. Sharing a sentence is not in itself a finding about the gene and the disease. The quoted sentences say what the papers report.
Desbuquois dysplasia type 1 (8 papers, 2012 to 2025). "Multiple joint dislocations are a clinical feature of Desbuquois dysplasia type 1 caused by human CANT1 mutations." (PMID 40141107, 2025). "Desbuquois dysplasia type 1 (DBQD1) results from homozygous or compound heterozygous mutations in the calcium-activated nucleotidase 1 (CANT1) gene." (PMID 39273648, 2024). "Cant1-deficient mice recapitulated the human phenotype of patients with Desbuquois dysplasia type 1, with short stature, thoracic kyphosis, and delta phalanx." (PMID 34220933, 2021). "Mutations in CANT1 cause Desbuquois dysplasia type 1 characterized by severe pre-natal and post-natal growth retardation with short extremities, joint laxity, and progressive scoliosis." (PMID 34220933, 2021). "•Desbuquois dysplasia type 1 (DBQD1) is a recessive skeletal dysplasia caused by mutations in CANT1 gene, a Calcium activated nucleotidase of the ER/Golgi." (PMID 30439444, 2019). "We immortalized primary chondrocytes from a Cant1 knock-out mouse, an animal model of Desbuquois dysplasia type 1, with a plasmid expressing the SV40 large and small T antigen." (PMID 34502207, 2021). "We recently generated a Cant1 knock-out mouse for the human Desbuquois dysplasia type 1 (DBQD1)." (PMID 34502207, 2021).
prostate carcinoma (8 papers, 2015 to 2024). A carcinoma that arises from epithelial cells of the prostate gland. "High expression of CANT1 in prostate cancer cells has been associated with better prognosis, while its silencing significantly suppressed cell proliferation and DNA synthesis." (PMID 37260986, 2023). "A number of the top genes identified in this study have previously been implicated in prostate cancer development and progression, Gleason grade, metastases and biochemical recurrence; including CANT1, FBP1, RRM2, POLE2, PDE4D, and ALDH1A3." (PMID 27980733, 2016). "CANT1 encodes the androgen-regulated protein CANT1, which has previously been found to form a fusion transcript with ETV4 in prostate cancer." (PMID 39010058, 2024). "The result from the analysis with the cancer multi-tissue network and the prostate cancer GWAS analysis included the gene CANT1 (p-value: 2.0 × 10− 6)." (PMID 39010058, 2024). "It has been demonstrated that CANT1 is involved in tumor growth: it is overexpressed in prostate cancer, lung squamous cell carcinoma, lung adenocarcinoma, and hepatocellular carcinoma." (PMID 39334831, 2024). "CANT1 is a new oncogenic mRNA in some cancer types, like human clear cell renal cell carcinoma (ccRCC) and prostate cancer." (PMID 35090419, 2022). "Nevertheless, the role of CANT1 has been confirmed in other cancers, including clear cell renal cell carcinoma (ccRCC) and prostate cancer." (PMID 35090419, 2022).
Desbuquois dysplasia (6 papers, 2019 to 2024). Desbuquois syndrome (DBQD) is an osteochondrodysplasia characterized by severe micromelic dwarfism, facial dysmorphism, joint laxity with multiple dislocations, vertebral and metaphyseal abnormalities and advanced carpotarsal ossification. "Mutations in the CANT1 gene play a pivotal role in the pathogenesis of Desbuquois dysplasia, which is also reflected in their significance in various types of cancers, such as lung and kidney cancer." (PMID 39273648, 2024). "Further research is needed to more precisely determine how mutations in CANT1 affect bone tissue development and function in Desbuquois dysplasia." (PMID 39273648, 2024). "Postnatal genetic testing confirmed our suspicion of Desbuquois dysplasia (type 1) due to a mutation of the 613,165 calcium-activated nucleotidase 1 (CANT1) gene." (PMID 33032557, 2020). "Mutations in the gene encoding for CANT1 (calcium‐activated nucleotidase 1) are responsible for Desbuquois dysplasia (DD) type 1." (PMID 32277574, 2020). "The identification of these compound heterozygous variants in CANT1 revealed a blended phenotype caused by a pathogenic and possibly pathogenic variations, leading to overlapping clinical features of Multiple Epiphyseal Dysplasia and Desbuquois Dysplasia." (PMID 31847883, 2019). "The high frequency of missense mutations in CANT1 in patients with Desbuquois dysplasia suggests that disruptions in this gene’s function may lead to significant alterations in bone development, similar to how they influence cancer progression through signaling pathways, such as NF-κB." (PMID 39273648, 2024). "This has been documented for B3GALT6-CDG (Al-Gazali syndrome, MIM: 609465), and CANT1-CDG (Desbuquois dysplasia, MIM: 251450), among others." (PMID 37858231, 2023). "Although the mechanisms in Desbuquois dysplasia differ from those observed in oncology, the potential of CANT1 as a biomarker suggests that it may also be significant in the diagnosis or prognosis of this condition." (PMID 39273648, 2024). "Thus, experience from studies on CANT1 in cancer may serve as a valuable reference point in the context of genetic disorders such as Desbuquois dysplasia." (PMID 39273648, 2024).
hepatocellular carcinoma (5 papers, 2015 to 2024). A malignant tumor that arises from hepatocytes.
lung adenocarcinoma (4 papers, 2022 to 2024). A carcinoma that arises from the lung and is characterized by the presence of malignant glandular epithelial cells. "High amplification of CANT1 was observed in lung adenocarcinoma (LUAD) and lung squamous cell carcinoma (LUSC) tissues compared to normal tissues." (PMID 35068336, 2022). "However, the potential clinical value of CANT1 in lung adenocarcinoma (LA) has not been fully clarified." (PMID 35090419, 2022).
multiple epiphyseal dysplasia (4 papers, 2019 to 2025). Multiple epiphyseal dysplasias (MED/EDMs) are characterized by epiphyseal anomalies causing joint pain early in life, recurrent osteochondritis and early arthrosis. "Studies have shown that CANT1 mutation is present in bone dysplasia (DD) and multiple epiphyseal dysplasia (MED), which are autosomal negative genetic diseases characterized by short metacarpal bones and long phalanges." (PMID 37858061, 2023).
chondrodysplasia (3 papers, 2019 to 2024). "Desbuquois dysplasia type 1 (DBQD1) is a recessive chondrodysplasia caused by mutations in the CANT1 gene, encoding for the Golgi Calcium-Activated Nucleotidase 1 (CANT1)." (PMID 39334831, 2024). "Desbuquois dysplasia type 1 (DBQD1) is a chondrodysplasia caused by mutations in CANT1 gene encoding an ER/Golgi calcium activated nucleotidase 1 that hydrolyses UDP." (PMID 30439444, 2019).
clear cell renal cell carcinoma (3 papers, 2020 to 2023). "In clear cell renal carcinoma, CANT1 silencing inhibited the proliferation, migration, and invasion of cells." (PMID 37858061, 2023). "CANT1 silencing suppressed clear cell renal cell carcinoma cell proliferation, migration, and invasion, which arrested the cell cycle in the S phase, and promoted apoptosis." (PMID 37858061, 2023).
lung carcinoma (3 papers, 2021 to 2023). "The current work aims to study the CANT1 role in lung cancer and understand the underlying pathological mechanisms." (PMID 35068336, 2022). "To address this assumption, we first analyzed CANT1 expression status and prognostic association with lung cancer individuals by a series biotinformatics analysis." (PMID 35068336, 2022). "To further elucidate the role of CANT1 in lung cancer, we established a xenograft model bearing CANT1-deficient H1299 cells or normal H1299 cells." (PMID 35068336, 2022). "In lung cancer, CANT1 promoted the progression of lung cancer by driving the nuclear factor-k gene binding (NF-κB) signaling pathway." (PMID 37858061, 2023). "Considering the possible interaction of CANT1 and NF-ĸB in glycosylation of lung cancer cells, we further checked the effect of CANT1 on NF-ĸB signaling." (PMID 35068336, 2022). "In conclusion, highly amplified CANT1 promotes the proliferation and viability of lung cancer cells." (PMID 35068336, 2022). "We also elucidate a new signaling axis of CANT1-NF-ĸB in lung cancer." (PMID 35068336, 2022). "Additionally, the effect of CANT1 to NF-ĸB signaling pathway involved in lung cancer cells was also ascertained." (PMID 35068336, 2022). "Overall, our findings indicated the role of CANT1 in lung cancer development." (PMID 35068336, 2022). "Additionally, the regulatory mechanism of CANT1 in lung cancer is complex; further work will focus on it." (PMID 35068336, 2022). "Taken together, CANT1 functioned as an oncogene in lung cancer tumorigenesis and progression." (PMID 35068336, 2022). "Some of these genes were previously shown to be prognostic biomarkers in different tumors, for example, high CANT1 expression was related to a poor prognosis in prostate and lung carcinomas, and PLS3 may be useful as a biomarker for identifying recurrences or a poor prognosis in some cancers." (PMID 34076352, 2021). "Therefore, we hypothesized that CANT1 drive lung cancer progression by the NF-ĸB signaling pathway." (PMID 35068336, 2022).
lung squamous cell carcinoma (3 papers, 2022 to 2024). "In squamous cell lung carcinoma, mir-607/CANT1 played an important role in its progression by mediating the EMT process, and was associated with poor prognosis." (PMID 37858061, 2023). "CANT1 was elevated in lung squamous cell carcinoma(LUSC), and knockdown of CANT1 blocked LUSC cell proliferation." (PMID 37858061, 2023).
neuroblastoma (3 papers, 2020 to 2025). Neuroblastoma (NB) is the most common solid, extracranial childhood tumor. "Further studies in neuroblastoma cells have demonstrated that CANT1 is a target gene of the DREAM protein, a Ca2+-dependent transcriptional repressor, and its activity is essential to the correct ER protein folding and degradation processes." (PMID 39334831, 2024). "CANT1 may be involved in glycan synthesis beyond GAGs and has also been reported to be involved in protein quality control and folding in neuroblastoma cell lines." (PMID 40141107, 2025). "Due to the etiology of eye neoplasms differing markedly from cutaneous melanomas and neuroblastomas, it is not surprising that the CANT1 isoform exists in RB and acts as a tumor suppressor that affects the characteristics of RB." (PMID 32366932, 2020).
scoliosis (3 papers, 2020 to 2021). A congenital or acquired spinal deformity characterized by lateral curvature of the spine. "The skeletal defects in our Cant1 KO mice were almost the same as in KO mice previously generated by the ES cell‐based method and are similar to those of DD type 1 patients, including short stature, progressive scoliosis, and delta phalanx." (PMID 32277574, 2020).
breast carcinoma (2 papers, 2018 to 2026). "Glycosylation-related enzymes such as calcium-activated nucleotidase 1 (CANT1) and Beta-1,3-N-acetylglucosaminyltransferase 3 (B3GNT3) have been implicated in tumour progression, yet their roles in breast cancer, particularly invasive ductal carcinoma (IDC), are not well defined." (PMID 41540462, 2026).
malignant melanoma (2 papers, 2015 to 2023). "For instance, CANT1 is known to regulate pyrimidine metabolism in melanoma cells and is associated with tumor progression." (PMID 37260986, 2023).
amelogenesis imperfecta (1 paper, 2021). Amelogenesis imperfecta (AI) represents a group of developmental conditions affecting the structure and clinical appearance of the enamel of all or nearly all the teeth in a more or less equal manner, and which may be associated with morphologic or biochemical changes elsewhere in the body. "Even if few features are typical for some disorders, characteristic hand anomalies in CANT1, IMPAD1, CHSY1, and TGDS-related conditions or amelogenesis imperfecta in dysplasia due to mutations in SLC10A7, for example, may help clinicians to orientate the clinical diagnosis." (PMID 34220933, 2021).
E. coli infection (1 paper, 2022). "As indicated by the enrichment analysis, CANT1 was functionally related to glycan biosynthesis, DNA replication, graft versus host disease, pathogenic E. coli infection, Leishmania infection, and cell cycle." (PMID 35068336, 2022). "In CANT1-high LC patients, GO terms enriched included Glycan biosynthesis, DNA replication, Graft versus host disease, pathogenic E. coli infection, Leishmania infection, and cell cycle." (PMID 35068336, 2022).
leukemia (1 paper, 2020). A malignant (clonal) hematologic disorder, involving hematopoietic stem cells and characterized by the presence of primitive or atypical myeloid or lymphoid cells in the bone marrow and the blood. "In addition, there were no studies of CANT1, KIAA1549, and NFIB on leukemia in previous literatures; therefore, the association between these genes and leukemia should be further investigated." (PMID 32638549, 2020).
liver cancer (1 paper, 2023). An epithelial or non-epithelial malignant neoplasm that arises from the liver. "CANT1 overexpression leads to downregulation of cytotoxic cells, which leads to the occurrence of liver cancer." (PMID 37858061, 2023). "Finally, the relationship between CANT1 and immune cell infiltration was analyzed, and the mechanism of CANT1 promoting liver cancer development was comprehensively studied." (PMID 37858061, 2023).
retinoblastoma (1 paper, 2020). A malignant tumor that originates in the nuclear layer of the retina. "In this report, we show that CANT1 is silenced in retinoblastoma and thus hSET1 methyltransferase is recruited to the PI3Kγ promoter, promoting its H3K4 trimethylation and activating PI3Kγ expression." (PMID 32366932, 2020). "In addition, RNA FISH demonstrated that CANT1 RNA was abundant in the cell nucleus of human retina tissues, whereas very weak signals were observed in human retinoblastoma tissues." (PMID 32366932, 2020).
steatosis (1 paper, 2023). Increased lipid within the cytoplasm of cells. "The logistic regression model, -34.19 + 0.85 * QDPR*QDPR + 0.75 * CANT1*TYMP - 0.46 * THOP1*ALDH1A, achieved an AUC of 0.93 (95% CI: 0.63-0.99), with a sensitivity of 93% and specificity of 80% for detecting steatosis in individuals with PWS." (PMID 38034016, 2023).
uveal melanoma (1 paper, 2020). A melanoma derived from melanocytes of the uveal tract. "We previously reported that lncRNA CANT1 triggers a CANT1-JPX/FTX-XIST long noncoding pathway to suppress uveal melanoma progression." (PMID 32366932, 2020).
ventricular septal defect (1 paper, 2025). The presence of a defect (opening) in the septum that separates the two ventricles of the heart. "The patient with a novel homozygous pathogenic CANT1 variant and ventricular septal defect (VSD) (patient 7) exhibited dysmorphic features similar to those reported in other VSD cases in the literature." (PMID 40461715, 2025).